UNC119 (unc-119 lipid binding chaperone)
Description:
Involved in synaptic functions in photoreceptor cells, the signal transduction in immune cells as a Src family kinase activator, endosome recycling, the uptake of bacteria and endocytosis, protein trafficking in sensory neurons and as lipid-binding chaperone with specificity for a diverse subset of myristoylated proteins. Specifically binds the myristoyl moiety of a subset of N-terminally myristoylated proteins and is required for their localization. Binds myristoylated GNAT1 and is required for G protein localization and trafficking in sensory neurons. Probably plays a role in trafficking proteins in photoreceptor cells. Plays important roles in mediating Src family kinase signals for the completion of cytokinesis via RAB11A.
Synonyms: hRG4; POC7; POC7A; CORD24; IMD13
Tractability: Small molecule: a structure with a bound ligand is known. PROTAC: ubiquitination databases record sites on it; its protein half-life has been measured.
Gene: Protein-coding gene on chromosome 17 (28,546,708 to 28,552,653, reverse strand). Ensembl gene ENSG00000109103.
Subcellular location: Cytoplasm, cytoskeleton, microtubule organizing center, centrosome; Cytoplasm, cytoskeleton, spindle pole; Cytoplasm, cytoskeleton, spindle
Gene Ontology:
Molecular function: lipid binding; protein binding
Biological process: lipoprotein transport; mitotic cytokinesis; positive regulation of protein tyrosine kinase activity; chemical synaptic transmission; negative regulation of caveolin-mediated endocytosis; negative regulation of clathrin-dependent endocytosis; nervous system development; phototransduction; visual perception
Cellular component: centrosome; intercellular bridge; spindle midzone; spindle pole; cytosol; spindle; synapse
Genetic constraint (gnomAD): Loss-of-function variants: 15 observed, 20.28 expected, observed/expected ratio (o/e) 0.74, 90% interval 0.49 to 1.14. The upper end of that interval is the gene's LOEUF score, 1.14, which puts it in group 4 of 6, group 1 being the genes least tolerant of losing a copy. Missense variants: 322 observed, 310.78 expected, observed/expected ratio (o/e) 1.04, 90% interval 0.94 to 1.14. Synonymous variants: 138 observed, 125 expected, observed/expected ratio (o/e) 1.1, 90% interval 0.96 to 1.27.
Homologues: Orthologues: chimpanzee UNC119 (99% identical), macaque UNC119 (97% identical), dog UNC119 (93% identical), rat Unc119 (92% identical), mouse Unc119 (92% identical), guinea pig UNC119 (86% identical), pig UNC119 (80% identical), zebrafish unc119a2 (66% identical), tropical clawed frog unc119 (66% identical), zebrafish unc119a1 (64% identical), rabbit UNC119 (59% identical), Drosophila melanogaster unc-119 (52% identical), and 1 more. Paralogues in human: UNC119B (56% identical).
Diseases named in the same sentence as UNC119 in open-access papers:
UNC119 is named in the same sentence as 43 diseases in open-access papers, as found by Europe PMC text mining. Sharing a sentence is not in itself a finding about the gene and the disease. The quoted sentences say what the papers report.
retinal degeneration (7 papers, 2014 to 2025). Degeneration of the retina. "Truncation mutations in UNC119 are detected in human patients and can lead to retinal degeneration in transgenic mice." (PMID 38303056, 2024). "Truncation mutation in UNC119 is linked to cone-rod dystrophy in human patients, whereas knockout of UNC119 in mice causes slow retinal degeneration." (PMID 33173469, 2020). "An Unc119 nonsense mutation was found in a patient with cone rod dystrophy and causes retinal degeneration in mice, which is consistent with the toxicity we observed upon Unc119 knockdown in cortical and hippocampal neurons." (PMID 25120191, 2014). "Unc119-deficient mice exhibit a slowly progressive retinal degeneration." (PMID 33681987, 2021). "Therefore, for ARL3-G70E, in addition to deficient ciliary INPP5E, altered PDE6δ and UNC119 function caused by aberrant ARL3-GTP cycling within the cell could also contribute to retinal degeneration." (PMID 40037334, 2025). "In addition, UNC119, which was originally identified in a screen for candidate retinal degeneration genes, predominates in the photoreceptor IS and synaptic regions and is essential for transducin trafficking toward the OS." (PMID 35698136, 2022). "Consistent with Unc119 and Pde6d deficiency, Arl3 conditional knockout mice show trafficking defects of lipidated proteins including rTα, rTγ, rod PDE6 and GRK1 to outer segments in rod photoreceptors and subsequent retinal degeneration." (PMID 33681987, 2021).
colorectal cancer (4 papers, 2017 to 2025). A primary or metastatic malignant neoplasm that affects the colon or rectum. "This dependence on UNC119 for proliferation has previously been shown in colorectal cancer cell lines, which rely on LCK signalling considerably less than T-ALL cells do." (PMID 39814552, 2025).
Cone rod dystrophy (3 papers, 2008 to 2020). "RRG4 mRNA (UNC119 - HRG4) was found down-regulated after neonatal brain ischemia/hypoxia, and mutations in this gene cause a rare form of cone-rod dystrophy - CRD (OMIM 604011)." (PMID 18334927, 2008).
retinal disease (3 papers, 2016 to 2024). ",62UNC119 is mainly involved in regulating the function of photoreceptor cells in the retina, and mutations in UNC119 can lead to neurodegenerative disorders, including retinal diseases." (PMID 39728691, 2024). "HRG4/Unc119 was mapped to chromosome 17q11.2 within the locus previously associated with inherited retinal disease." (PMID 36982165, 2023). "We did not evaluate the expression of several retinal disease-related genes such as UNC119 and BBS5 because of their strong expression in primary PBMCs or their ubiquitous expression in other regions besides the retina." (PMID 27170256, 2016).
ciliopathy (2 papers, 2016 to 2022). A genetic disorder of the cellular cilia or the cilia anchoring structures, the basal bodies, or of ciliary function. "The findings reveal a novel mechanism that one ciliopathy GTPase ARL-13, as a GEF, coordinates with UNC-119, which may act as a GTP-binding stabilizing factor, to properly activate another GTPase ARL-3 in cilia, a regulatory process indispensable for ciliogenesis." (PMID 27102355, 2016).
acute lymphocytic leukaemia (1 paper, 2025). "UNC119 also may represent a therapeutic target in T acute lymphocytic leukaemia as UNC119 inhibition reduced cancer cell growth." (PMID 39814552, 2025). "UNC119 may therefore represent a novel therapeutic target in T acute lymphocytic leukaemia, which alters the subcellular localisation of LCK in T acute lymphocytic leukaemia cells but preserves the function of existing cytotoxic lymphocytes." (PMID 39814552, 2025).
colorectal tumour (1 paper, 2017). "We investigated whether perturbation of SFK localisation by UNC119 KD affected the growth of SFK-dependent colorectal tumour cells." (PMID 28740133, 2017).
Joubert syndrome (1 paper, 2021). Joubert syndrome (JS) is characterized by congenital malformation of the brainstem and agenesis or hypoplasia of the cerebellar vermis leading to an abnormal respiratory pattern, nystagmus, hypotonia, ataxia, and delay in achieving motor milestones. "In contrast, the Joubert syndrome cluster contained five hits found under starved conditions, CPLANE1, UNC119, PIBF1, and CEP164." (PMID 34685691, 2021).
lymphoma (1 paper, 2025). A malignant (clonal) proliferation of B- lymphocytes or T- lymphocytes which involves the lymph nodes, bone marrow and/or extranodal sites. "As such, we next quantified cytotoxic killing of lymphoma cells by Unc119-inhibited CTLs in vitro." (PMID 39814552, 2025). "It was next important to determine the role of Unc119 in TCR signal transduction, and so, we formed immune conjugates in vitro using OTI CD8+ T cells and SIINFEKL-expressing EG.7 lymphoma cells and quantified the polarisation of total LCK and pLCK Y394 to the IS as represented schematically." (PMID 39814552, 2025).
Retinal dystrophy (1 paper, 2025). Retinal dystrophy is an abnormality of the retina associated with a hereditary process. "Of these patients, seven had monoallelic pathogenic variants in ABCA4, one had biallelic variants of uncertain significance (VUS) in ABCA4, two had monoallelic VUS in ABCA4, and eight harbored VUS in other retinal dystrophy-related genes, including KCNV2, RIMS1, CRB1, CFH, RP1L1, UNC119, and SEMA4A." (PMID 41234456, 2025).
shigellosis (1 paper, 2009). Shigellosis is a bacterial infection leading to dysentery and is caused by Shigella, which are small, ubiquitous Gram-negative bacteria belonging to the enterobacteria family. "To demonstrate that Unc119 plays a role in Shigella pathogenesis in vivo we performed a proof-of-concept experiment in a mouse model of shigellosis." (PMID 19381274, 2009).
type 2 diabetes (1 paper, 2019). "UNC119 is also located on chromosome 17, together with TSEN54 and CDK5R1, known for sight-threatening retinopathy in type 2 diabetes and disturbed retinal morphology, respectively." (PMID 30718923, 2019).
infection (5 papers, 2009 to 2024). The state of being infected such as from the introduction of a foreign agent such as serum, vaccine, antigenic substance or organism. "The co-localization of Unc119-GFP with Shigella was highest at 30 minutes after the start of infection with 40% of the total internalized bacteria associated with Unc119-GFP." (PMID 19381274, 2009). "We propose the induction of Unc119 as a novel approach to boosting host defense and fighting infection." (PMID 19381274, 2009). "Unc119 induction in vivo boosts host defense against infections." (PMID 19381274, 2009). "We speculate that the upregulation of Unc119 by Shigella is a homeostatic response that is aimed at preventing further infection." (PMID 19381274, 2009). "We wondered whether Unc119 was an inducible protein and regulated by factors that secondarily affected infection." (PMID 19381274, 2009). "Fyn was not significantly activated during infection in normal cells but was strongly activated in Unc119 overexpressing cells." (PMID 19381274, 2009). "We speculate that this Unc119-mediated inhibition represents a non-immunologic recovery mechanism in certain infections." (PMID 19381274, 2009).
tumor (4 papers, 2016 to 2026).
bacterial infection (1 paper, 2009). "To explore if the Unc119 mediated regulation of bacterial infection is dependent upon SFKs, we used the SFK deficient SYF fibroblast cell line, which lacks Src, Yes and Fyn kinases." (PMID 19381274, 2009). "We explored the activation of Fyn, a ubiquitously expressed SFK, during the bacterial infection in 3T3 cells overexpressing Unc119." (PMID 19381274, 2009). "Next, we studied the activation of Abl kinases and Crk phosphorylation during bacterial infection in cells overexpressing Unc119." (PMID 19381274, 2009). "To identify proteins that interact with Unc119 and thus affect bacterial infection, we screened for Unc119 interactive SH3 domain-containing proteins using a TranSignal SH3 domain array." (PMID 19381274, 2009). "To study the effect of Unc119 on bacterial infection, we knocked down Unc119 expression by 70–90% in human epithelial cells (Caco2 and HeLA) and mouse embryonic fibroblasts (NIH 3T3, abbreviated as 3T3) using siRNA and then infected them with Shigella flexneri." (PMID 19381274, 2009). "Indeed, tyrosine phosphorylation of Crk (Y221) by Shigella infection and to a lower extent, phosphorylation of CrkL by PDGF was decreased in Unc119 overexpressing cells at 15 and 30 min after bacterial infection." (PMID 19381274, 2009). "To examine whether Unc119 upregulation is one of the mechanisms by which sodium butyrate decreases the bacterial infection we treated Unc119 knockdown mice with butyrate and studied Shigella infection." (PMID 19381274, 2009). "However, in the absence of Unc119 butyrate was ineffective in decreasing the bacterial infection indicating that Unc119 plays an essential role in mediating the protective effect of butyrate." (PMID 19381274, 2009). "We assumed that Unc119 would promote bacterial infection because of its role in SFK activation." (PMID 19381274, 2009). "In the absence of all SFKs, Unc119 knockdown still doubled the bacterial infection in the SYF cell line." (PMID 19381274, 2009). "In Abl−/− and Arg−/− cells the bacterial infection increased in the absence of Unc119 to a degree that was similar to that observed in control cells." (PMID 19381274, 2009). "However, in Abl−/−Arg−/− cells the bacterial infection was unaffected by the absence of Unc119." (PMID 19381274, 2009).
UNC119 also shares sentences with these, for which no sentence is quoted: cancer (13 papers); breast carcinoma (5); neurodegenerative disease (4); COVID-19 (3); Alzheimer disease (2); glioblastoma (2); virus infection (2); amyotrophic lateral sclerosis (1); brain ischemia (1); hair loss (1); hemorrhagic stroke (1); immunity disorder (1); immunodeficiency disorder (1); infectious disease (1); Infertility (1); Lewis lung carcinoma (1); malaria (1); melanoma (1); onychomycosis (1); osteosarcoma (1); otitis media (1); pneumonia (1); prion disease (1); retinopathy (1); sarcoma (1); Sepsis (1); sinusitis (1); subarachnoid hemorrhage (1).